PFKFB3 (6-phosphofructo-2-kinase/fructose-2,6-biphosphatase 3)
Diseases named in the same sentence as PFKFB3 in open-access papers (continued):
Sharing a sentence is not in itself a finding about the gene and the disease.
Sepsis (continued). "In addition, there is a new research focus on the role of PFKFB3-driven glycolysis in neutrophil inflammatory activation in immune metabolism and sepsis." (PMID 37199341, 2023). "Therefore, the targeted inhibition of PFKFB3-driven glycolysis in macrophages is a potential therapeutic strategy for avoiding inflammatory injury in sepsis." (PMID 37199341, 2023). "Thus, all of these studies demonstrate that PFKFB3-driven glycolysis plays a critical role in sepsis-induced endothelial inflammation." (PMID 37199341, 2023). "Furthermore, increased PFKFB3 is closely related to the excessive inflammatory response and high mortality in sepsis." (PMID 37199341, 2023). "Likewise, zinc fingers and homeoboxes (Zhx2) have been confirmed to be involved in sepsis by promoting the expression of 6-phosphofructo-2-kinase/fructose-2,6-biphosphatase 3 (Pfkfb3), thereby increasing glycolysis." (PMID 35847986, 2022). "Therefore, we explored the effects of Gsdmd gene deletion and PFKFB3 inhibitor, 3PO, on intestinal damage in sepsis." (PMID 36589684, 2022). "Therefore, our study suggested that GSEC-regulated PFKFB3-mediated glycolytic reprogramming is a potential sepsis therapeutic target." (PMID 34907156, 2021). "Also, PFKFB3 is involved in alleviating sepsis-related acute lung injury via suppressing inflammation and apoptosis of alveolar epithelial cells." (PMID 34021541, 2021). "Therefore, PFKFB3 is a potential target for the prevention and treatment of inflammatory diseases such as sepsis." (PMID 34660743, 2021). "In the present study, we demonstrated the effect of myeloid Pfkfb3 in LPS-induced sepsis in mice." (PMID 34660743, 2021). "We examined whether the sepsis-associated inflammatory stimuli lipopolysaccharide (LPS) and TNF-α regulate the expression of GSEC and PFKFB3 mRNA in neutrophils in vitro." (PMID 34907156, 2021). "The enzyme 6-phosphofructo-2-kinase/fructose-2,6-bisphosphatase isoform 3 (PFKFB3) is a critical regulator of glycolysis and plays a key role in modulating the inflammatory response, thereby contributing to the development of inflammatory diseases such as sepsis." (PMID 38705396, 2024). "Interestingly, the meta-analysis data also revealed an increased abundance of PFKFB3 in sepsis." (PMID 38705396, 2024). "Therefore, understanding how to regulate glycolysis reprogramming and PFKFB3 expression could provide valuable insights for improving sepsis treatments." (PMID 38705396, 2024). "Therefore, efforts to understand PFKFB3 may provide a novel combinatorial therapeutic target for the effective treatment of sepsis." (PMID 37199341, 2023). "Thus, PFKFB3 has become a novel therapeutic target for inhibiting excessive inflammation in sepsis." (PMID 37199341, 2023). "Taken together, our results suggest that PFKFB3 is involved in inflammation, oxidative stress, and pyroptosis during sepsis and enhances intestinal damage, which may provide important clues about the potential targets to be exploited in this highly lethal disease." (PMID 36589684, 2022). "Hence, PFKFB3-dependent aerobic glycolysis may act as a key regulator in the pathogenesis of intestinal barrier dysfunction in sepsis." (PMID 36589684, 2022). "Data from genome-wide gene expression profiles show that Pfkfb3 (6-phosphofructo-2-kinase/fructose-2,6-bisphosphatase 3) is the most upregulated gene among the glycolytic genes in LPS-stimulated macrophages, indicating a potential role of PFKFB3 in LPS-induced sepsis." (PMID 34660743, 2021). "However, it remains unclear whether decreased macrophage glycolysis via Pfkfb3 inactivation can suppress macrophage inflammation and protect mice from LPS-induced sepsis." (PMID 34660743, 2021). "Second, as macrophages are critical in the host response to infection, thereby, it remains unclear whether blocking of macrophage glycolysis and cytokine production by deletion of Pfkfb3 would impair the role of macrophages in bacterial clearance and resolution of infection-mediated sepsis." (PMID 34660743, 2021).
Sepsis (continued). "The qPCR results suggest that GK and PFKFB3 might contribute to the progression of S. aureus-induced sepsis, and CEACAM1, TNFAIP6, PSTPIP2, SOCS3, and IL18RAP might be closely linked with E. coli-induced sepsis." (PMID 31093495, 2019). "The qPCR results suggested that GK and PFKFB3 might contribute to the progression of S. aureus-induced sepsis, and GK, CEACAM1, TNFAIP6, PSTPIP2, SOCS3, and IL18RAP might be closely linked with E. coli-induced sepsis." (PMID 31093495, 2019). "Under hypoxic conditions in sepsis, HIF-1α acts as a key upstream molecule in glycolysis, promoting the expression of key glycolytic enzymes such as GLUT1, HK2, and PFKFB3." (PMID 39712019, 2024). "In addition to these transcriptional mechanisms, our research found that in sepsis, Pfkfb3 upregulation in monocytes and macrophages is also posttranscriptionally regulated by miR-106a-5p, with a decrease in miR-106a-5p during sepsis leading to the stabilization of Pfkfb3 mRNA." (PMID 38705396, 2024). "This review summarizes the role of PFKFB3-driven glycolysis in the regulation of immunocyte activation and nonimmune cell damage in sepsis." (PMID 37199341, 2023). "In addition, metabolism-related genes, including PFKFB3, PRKAA1, PYGL, and GYG1, were also upregulated, which indicated their potential roles in mediating immune responses in sepsis." (PMID 34907156, 2021). "Targeted knockout of PFKFB3 leads to a significant reduction in EC glycolysis and effectively inhibits the NF-κB and HIF-1α signalling-mediated endothelial inflammatory response, thereby impeding the onset and progression of pulmonary hypertension, sepsis, and acute lung injury in murine models." (PMID 38755659, 2024). "No studies have been reported on PFKFB3-driven glycolysis and other immunocytes in sepsis." (PMID 37199341, 2023). "For example, it is still not known whether the metabolic timelines of PFKFB3-driven glycolysis in different immune and nonimmune cells in sepsis are consistent." (PMID 37199341, 2023). "Also, PFKFB3 has been shown to be a target of the zinc fingers and homeoboxes 2 (ZHX2) transcription factor and, as a result, to accelerate disease progression in models of sepsis." (PMID 34044589, 2021). "Therefore, an improved understanding of the canonical and noncanonical functions of PFKFB3 may provide a novel combinatorial therapeutic target for sepsis." (PMID 37199341, 2023). "However, the effect of myeloid Pfkfb3 on modulation of LPS-induced sepsis has not been studied yet." (PMID 34660743, 2021).
diabetes (26 papers, 2013 to 2025). "PFKFB3 as a glucose regulator and is associated with diabetes and cancer." (PMID 38184549, 2024). "PFKFB3 encodes a pro-glycolytic enzyme that is upregulated in cardiac progenitor cells by diabetes." (PMID 29556499, 2018). "The temporally dynamic, context-dependent role of PFKFB3 should be carefully considered when targeting metabolic pathways for diabetes therapy." (PMID 40600018, 2025). "Our work highlights the temporally dynamic role of PFKFB3 in beta cell physiology and underscores the importance of context when targeting metabolic pathways for diabetes therapy." (PMID 40600018, 2025). "Nevertheless, chronic inflammation in diabetes suppresses NK cells allowing potentially PFKFB3 “loser” β-cells to bypass the immunosurveillance." (PMID 39313296, 2024). "Recent studies have reported the widespread tissue expression of PFKFB3 and its involvement in various physiological processes, such as tumorigenesis, metastasis, diabetes-related organ damage, and angiogenesis." (PMID 39356055, 2024). "Pathologic β-cells become long-lived in diabetes despite high energy conservation based on the control over their metabolic state via PFKFB3 and suppression of Ca2+ toxicity via MAIP1." (PMID 39313296, 2024). "The diabetes significant PFKFB3 SNP at the 10p15.1 locus (rs1983890) interacted with MAIP1 and AGAP1 collective SNPs in GGI analysis." (PMID 39313296, 2024). "Although we have not found transcriptional up-regulation of PFKFB3 in the “loser” HPAP datasets, we found that APC/Cdh1 E3 ubiquitin ligase that regulates PFKFB3 stability was down-regulated in T2DHPAP, in line with PFKFB3 protein up-regulation in diabetes." (PMID 39313296, 2024). "We reported that activation of HIF1α–PFKFB3 in rodent models of prediabetes preceded chronic glycolytic energy production, which further exacerbated the slip of β-cells into decompensation and diabetes progression." (PMID 35318430, 2022). "In conclusion, diabetic retinas display a decreased glycolytic response during the early course of diabetes which is accompanied by a reduction in PFKFB3." (PMID 35722112, 2022). "Mice with streptozotocin (STZ)-induced diabetes had significantly higher PFKFB3 expression in pancreatic beta cells than control-treated mice (p <0.001), which was significantly inhibited by 3-(3-pyridinyl)-1-(4-pyridinyl)-2-propen-1-one (3PO), a glycolysis inhibitor (p <0.001)." (PMID 40600018, 2025). "Although increased PFKFB3 expression has been observed in pancreatic islets from individuals with long-standing diabetes, the functional significance of this upregulation may vary over time." (PMID 40600018, 2025). "To find out whether PFKFB3 is a gatekeeper of CFC in diabetes, we sought to establish whether PFKFB3-positive β-cells are identical to “loser” β-cells from CFC." (PMID 39313296, 2024). "In addition, miR-26/PFKFB3 was also shown to play a similar role in gastric cancer patients with diabetes." (PMID 36973739, 2023). "Compared with diabetes, miRNA-590-3p mimics treatment reduced the PFKFB3 presence in glomeruli." (PMID 37781737, 2023). "The induction of diabetes in PFKFB3-Mut mice was similar to that in IGFBP5−/− mice." (PMID 35418167, 2022). "However, there was a significant decrease in PKM2 after 17 weeks of diabetes, with PFKFB3 showing a trend toward reduction as well." (PMID 35722112, 2022). "PFKFB3 has been suggested to have a critical role in diabetes mellitus." (PMID 33520118, 2021). "Further investigation revealed that PROM1, TFPI2, and PFKFB3 are crucial genes involved in the regulation of IL11 expression in patients with kidney stones and diabetes." (PMID 37480086, 2023). "We identified 8 hub genes (JUN, ATF3, VEGFA, SLC2A1, HK2, PTGS2, PFKFB3, and KLF6) that were enriched in response to hypoxia, angiogenesis, vasculogenesis, hypoxia-induced signaling, cancer, diabetes, and transplant-related disease pathways." (PMID 36482897, 2022).
diabetes (continued). "Particularly, HIF-1α and its effector Pfkfb3 were activated in islets from individuals with T1DM and streptozotocin-induced diabetes mouse liver." (PMID 35955706, 2022). "Considering the beneficial effects of stevia in metabolic disorders and diabetes, the stevia-mediated reduction of hsCRP and ESR observed in the current study among CKD patients may suggest a potential interaction with PFKFB-3." (PMID 40821154, 2025). "Immunohistochemistry was adopted to analyze the protein level of PFKFB3 in benign breast tissues, invasive ductal carcinoma with diabetes and invasive ductal carcinoma without diabetes." (PMID 36973739, 2023). "The PFKFB3 expression level of benign breast tissues and invasive ductal carcinoma with/without diabetes were compared with IHC based on the multi-center cases we collected to ensure the reliability of the results." (PMID 36973739, 2023). "Furthermore, excessive levels of glycolytic markers, including PFKFB3, HK2, and other key glycolytic proteins, as well as overproduction of lactate, have been reported in vascular endothelial cells inflicted by atherosclerosis, diabetes mellitus, and other vascular lesion-related diseases." (PMID 36425580, 2022).
gastric cancer (25 papers, 2016 to 2025). A primary or metastatic malignant neoplasm involving the stomach. "PFKFB3, a key glycolytic enzyme, is closely linked to patient prognosis in gastric cancer." (PMID 41220952, 2025). "PFKFB3, a glycolytic enzyme, is highly expressed in various cancers, including gastric cancer, and its expression correlates with poor prognosis." (PMID 41220952, 2025). "Inhibition of PFKFB3 can reduce glycolytic activity and suppress tumor growth, making it a promising therapeutic target in gastric cancer treatment." (PMID 41220952, 2025). "PFK15, a small molecule inhibitor targeting the glycolytic rate-limiting enzyme PFKFB3, has demonstrated effectiveness in gastric cancer." (PMID 41220952, 2025). "Gastric cancer cells resistant to trastuzumab exhibit increased glycolysis, and 6-phosphofructo-2-kinase (PFKFB3) was shown to activate glycolytic pathways, resulting in distinct changes in the tumor microenvironment." (PMID 38611014, 2024). "Pfkfb3 has been shown to be highly expressed in various tumor cells, including pancreatic, breast, and gastric cancer." (PMID 38813509, 2023). "On the other hand, PFKFB3 modulates cell proliferation with the concomitant activation of NF-kB signaling in gastric cancer." (PMID 37919747, 2023). "PFKFB3 is frequently observed in pancreatic cancer, gastric cancer, nasopharyngeal carcinoma, and many other neoplasms." (PMID 37919747, 2023). "Our study confirmed the adverse effect of hyperglycemia on the prognosis of gastric cancer patients and first revealed that hyperglycemia promoted the malignant phenotype of gastric cancer cells via miR-26-5p/PFKFB3/TGF-β signaling pathway." (PMID 35094634, 2022). "Similar findings were observed using PFK15 (a small molecule inhibitor of PFKFB3) in gastric cancer cells." (PMID 33671514, 2021). "PKD3 also phosphorylates p65 at serine 536, a critical step for the up-regulation of 6-phosphofructo-2-kinase/fructose-2,6-biphosphatase 3 (PFKFB3) and drives glycolysis in gastric cancer cells." (PMID 34145024, 2021). "The protein abundance of PFKFB3 and G6PD was increased in gastric cancer tissues, which was associated with increased TNM stage." (PMID 31591390, 2019). "This was corroborated by our findings that pharmacological inhibition of glycolysis and the PPP reduced proliferation in gastric cancer cells, whereas overexpression of PFKFB3 and G6PD augmented proliferation in these cells." (PMID 31591390, 2019). "Along with the data on ECAR, lactate, and glucose consumption, Rev-erbα suppresses glycolytic flux and the PPP in gastric cancer cells by inhibiting PFKFB3 and G6PD gene expression." (PMID 31591390, 2019). "The objective of this study was to investigate the antitumor activity of PFK15 (1-(4-pyridinyl)-3-(2-quinolinyl)-2-propen-1-one), a small molecule inhibitor of PFKFB3, against gastric cancer and to explore its potential mechanisms." (PMID 27669567, 2016). "Another rescue experiment that F2,6P2 addition abrogated the PFK15-induced cell proliferation suppression in gastric cancer cells further supported the specificity of PFK15 for PFKFB3 enzyme." (PMID 27669567, 2016). "In this study, we investigated the antitumor activities of PFK15, a selective PFKFB3 inhibitor, and explored its potential mechanism of action in gastric cancer." (PMID 27669567, 2016). "Moreover, RORα expression inversely correlates with G6PD and PFKFB3, and low RORα combined with high G6PD or PFKFB3 predicts poor survival in gastric cancer, indicating RORα as a potential biomarker and therapeutic target." (PMID 41425709, 2025). "Monitoring PFKFB3 expression may assist clinicians in assessing gastric cancer patient prognosis and tailoring treatment strategies." (PMID 41220952, 2025). "Previous studies reported that PFKFB3 impacts cancer cell proliferation by regulating the expression levels or post-transcriptional modification levels of cyclin-dependent kinase and thus influences cell cycle arrest in gastric cancer and cervical cancer." (PMID 37253634, 2023).
gastric cancer (continued). "Consequently, PFKFB3 activating processes were correlated to exacerbation of glycolytic activity, with PFKFB3 also being up-regulated in multiple tumors including pancreatic, breast and gastric cancer." (PMID 35057732, 2022). "Functionally, knockdown of PFKFB3 results in a reduced migration rate of gastric cancer cells, a result consistent with our finding that manipulation of PFKFB3 in CSC-enriched/differentiated subsets affected the migration/invasion capacity of ovarian cancer in vitro." (PMID 35155224, 2022). "Further studies have shown that PFKFB3 mRNA was elevated in gastric cancer tissue compared to normal gastric tissue, as well as in gastric cancer cell lines (MKN45, NUGC3), and in head and neck squamous cell carcinoma (HNSCC) compared with adjacent mucosal tissue." (PMID 28977989, 2017). "PFKFB3 protein levels are overexpressed in a wide variety of cancers, including breast, prostate, colon, astrocytoma, ovarian, pancreatic and gastric cancers, and its expression or activity has been found to be strongly correlated with the aggressiveness and poor prognosis of the cancer." (PMID 27669567, 2016). "In summary, our study demonstrates that RORα inhibits gastric cancer proliferation by attenuating the glycolytic ability induced by G6PD and PFKFB3 in GC." (PMID 38184549, 2024). "H19 influences metabolic reprogramming by affecting the glycolytic enzymes such as 6-phosphofructo-2-kinase/fructose-2,6-biphosphatase 3 (PFKFB3) and LDHA, thereby altering glycolysis in oral and gastric cancers." (PMID 39806421, 2025). "In cancer cells, increased PFKFB3 levels activate the NF-κB pathway, promoting EMT and enhancing the migratory capacity of gastric cancer (GC) cells." (PMID 41278473, 2025). "In summary, these results indicate that RORα plays a crucial role in gastric cancer proliferation and glycolysis by modulating G6PD and PFKFB3 genes." (PMID 38184549, 2024). "This is corroborated by the findings that both PFKFB3 and G6PD are overexpressed in patients with gastric cancer, and promoted the proliferation and migration of gastric cancer cells." (PMID 31591390, 2019). "This suggests that both PFKFB3 and G6PD are required for proliferation when Rev-erbα was reduced in human gastric cancer cells." (PMID 31591390, 2019). "Both PFKFB3 and G6PD were overexpressed in patients with gastric cancer, and positively correlated with the TMN stages." (PMID 31591390, 2019). "To extrapolate the in vitro findings into human samples, we determine the expression of PFKFB3 and G6PD as well as the metabolites, including lactate, pyruvate and NADPH in patients with gastric cancer." (PMID 31591390, 2019). "In summary, we demonstrated for the first time that Rev-erbα was recruited to promoters of PFKFB3 and G6PD genes, thereby inhibiting glycolytic flux and the PPP, and subsequent proliferation in in vitro human gastric cancer cells." (PMID 31591390, 2019). "We found that mutation of Rev-erbα DBD domain increased the mRNA slevels of PFKFB3 and G6PD in human gastric cancer cell." (PMID 31591390, 2019). "Utilizing clinical human samples, we found that the protein abundance of PFKFB3 and G6PD was increased in patients with gastric cancer." (PMID 31591390, 2019). "Although Rev-erbα inhibited PFKFB3 and G6PD gene expression, it is unclear whether PFKFB3 and G6PD mediate the effect of Rev-erbα on proliferation of human gastric cancer cells." (PMID 31591390, 2019). "It remains elusive whether Rev-erbα inhibits PFKFB3 and G6PD gene expression using similar mechanisms in human gastric cancer cells." (PMID 31591390, 2019). "This was due to increased expression of PFKFB3 and G6PD in human gastric cancer cells." (PMID 31591390, 2019). "We found that Rev-erbα could be recruited on the promoters of PFKFB3, an isoform of PFK, and G6PD genes, and directly inhibited their gene transcription in human gastric cancer cells." (PMID 31591390, 2019).